STAT3 (signal transducer and activator of transcription 3)
Diseases named in the same sentence as STAT3 in open-access papers (continued):
Sharing a sentence is not in itself a finding about the gene and the disease.
breast cancer (continued). "In breast cancer, the PTEN/mTOR/STAT3 pathway plays a crucial role in cancer stem-like cell viability and stem maintenance." (PMID 31781676, 2019). "Next, we investigated the expression status of the Notch-1, β-catenin, STAT3, CD44, and CD24 markers in doxorubicin resistantMCF7 breast cancer cells (MCF7_DoxR) compared to MCF7 parental cells (MCF7_DoxS)." (PMID 31357721, 2019). "Lnc-BM induces STAT3-dependent expression of CCL2 to attract macrophages, thus enhancing breast cancer brain metastasis." (PMID 31448238, 2019). "Cancer-related adipose tissues can promote the progression of breast cancer through paracrine OSM and JAK/STAT3 signal transduction." (PMID 31871447, 2019). "Currently, abundant studies have reported that the STAT3 or p-STAT3 expression has close connection with the occurrence, differentiation, TNM stages and lymphatic metastasis of breast cancer." (PMID 31375715, 2019). "In the breast cancer cell line MDA-MB-231, overexpression or depletion of HIC1 resulted in decreased or increased levels of cytokine-induced STAT3-target gene RNA transcripts." (PMID 29914167, 2018). "Our study reveals that adipocyte-derived IL-6 and leptin promote PLOD2 expression by activating the JAK/STAT3 and PI3K/AKT signaling pathways, thus promoting breast cancer metastasis." (PMID 30563531, 2018). "The new and, in some aspects, revolutionary information that emerges is that, in some patients with breast cancer, inactivation of JAK/STAT3 signaling can, in some way, contribute to disease progression and metastasis." (PMID 30231553, 2018). "In breast cancer, PTPN9 indirectly inhibits activity of STAT3 and STAT5 through direct dephosphorylation of EGFR and HER2." (PMID 29558404, 2018). "Persistent prolactin receptor signalling has been shown in STAT1-deficient mammary epithelial cells, and this results in the activation of JAK2, STAT3 and STAT5A/5B, and the subsequent development of oestrogen receptor-α-positive mammary tumours." (PMID 29875329, 2018). "HGF is believed to act as an initiation signal for the onset of EMT, which results in the upregulation of effector molecules, such as MMP-2 and MMP-9, and activation of STAT-3 to aid EMT and the metastatic dissemination of breast cancer cells." (PMID 30314527, 2018). "STAT3 was found to increase the expression of BCL6 in breast cancer cells; however, the STAT5-mediated repression of BCL6 in these cells was dominant, because STAT5 displaced STAT3 from the shared DNA-binding site." (PMID 29728695, 2018). "Combined treatment of breast cancer cells with curcumin and epigallocatechin gallate (EGCG) reduced CD44-positive CSC population and decreased phosphorylated STAT3 expression." (PMID 29747682, 2018). "A 3-day exposure to leptin significantly increased PLOD2 expression and activated phosphorylation of STAT3 and AKT in MDA-MB-231 and MDA-MB-468 breast cancer cells." (PMID 30563531, 2018). "In breast cancer, activation of STAT-3 and STAT-5 is frequently observed in cancer cells, with STAT-3 often activated in invasive and metastatic tumors." (PMID 30373171, 2018). "Hypoxic breast cancer cells were treated with specific inhibitors of Akt (LY294002), MAPK (AG126), and STAT3 (PF04965842) followed by MAO-A and HIF-1α activities were measured." (PMID 29695771, 2018). "For instance, EZH2 activates NF-κB target genes in breast cancer, and in a subpopulation of glioblastoma stem cells, EZH2 methylates STAT3, leading to enhanced STAT3 activation." (PMID 29498629, 2018). "The STAT3, RAS/MEK/ERK and PI3K/AKT signaling pathways are often up-regulated in breast cancer cells and are fundamental to proliferation, differentiation, migration and invasion." (PMID 29707128, 2018).
breast cancer (continued). "To address the molecular mechanisms through which IL-6 and RANTES promote breast cancer cell migration and invasion, we analyzed their effects on the activation of ERK1/2, AKT and STAT3 signal transduction proteins at different time points." (PMID 29707128, 2018). "MDSCs in breast cancer have also been shown to induce Notch signaling in cancer cells and promote CSC capacity through IL6/STAT3 & Nitric Oxide/Notch cross talk signaling." (PMID 30515368, 2018). "Galiellalactone was only moderately active on STAT3-mediated luciferase activity with IC50 ≈ 5 μM and on cell growth with cytotoxic activities IC50 ≈ 10–20 μM against human breast cancer cell lines." (PMID 29921764, 2018). "Together, our results suggest that pharmacological inhibition of IL-6 and leptin as well as the downstream JAK/STAT3 and PI3K/AKT signaling pathways can decrease PLOD2 expression and suppress breast cancer metastasis." (PMID 30563531, 2018). "Inhibition of STAT3 activity using a pharmacological inhibitor of JAK (ruxolitinib) decreased PLOD2 expression in adipocyte cocultured MDA-MB-231 and MDA-MB-468 breast cancer cells." (PMID 30563531, 2018). "NANOG cooperates with STAT3 to maintain pluripotency and self-renewing cells, after down-regulation of NANOG, cell proliferation, colony formation, and migration are reduced in breast cancer cells." (PMID 30542507, 2018). "TFRG also markedly reduced tumor mass of breast cancer cell MDA-MB-231 xenografts with suppression of iNOS expression, formation of 3-nitrotyrosine (3-NT), and inactivation of protumorigenic JAK2/STAT3 signaling pathway." (PMID 29951107, 2018). "Ikeda and colleagues showed that BRK and STAP-2 are highly expressed in breast cancer cells and reported that STAP-2 is phosphorylated at tyrosine-250 by BRK, thus enhancing BRK-mediated STAT3 activation." (PMID 29914167, 2018). "The main goal of this study was to assess inhibition of tumor angiogenesis by nobiletin in estrogen receptor positive (ER+) breast cancer cells via Src, FAK, and STAT3-mediated signaling through PXN." (PMID 28468300, 2017). "The results from breast cancer confirmed those from metastatic melanoma, indicating FAK regulates E-cadherin expression via p-SrcY416/ p-ERK1/2/p-Stat3Y705 and PPARγ/miR-125b/Stat3 signaling pathway." (PMID 28108732, 2017). "Constitutive activation of STAT3 has also shown to accelerate tumor progression and increase the metastatic potential in HER2-positive breast cancers." (PMID 28607534, 2017). "JAK2/STAT3 signaling was also reported to be involved in GPER signaling in the hypothalamus and SKBR-3 breast cancer cells." (PMID 28301550, 2017). "To explore the potential upstream regulators for CSE, we firstly investigated the correlation between STAT3 and CSE expression in human breast cancer tissues and cells." (PMID 29029463, 2017). "Based on our previous findings that C10 significantly reduced IL-6 protein levels and STAT3 phosphorylated via TLR3 signaling in other cancers, we also evaluated these in MCF-7 breast cancer cells." (PMID 29371911, 2017). "Among them, STAT3 and STAT5 is indicated as the oncogene in the process of pathogenesis of BC, based on evidences from breast cancer cell lines, animal models, and primary human tissues." (PMID 28422733, 2017). "HMGA2 is part of a larger STAT3/LIN28/Let‐7/HMGA2 axis with important oncogenic functions in a subset of GB and breast cancer cells." (PMID 28500786, 2017). "Signal transducer and activator of transcription 3 (STAT3) is a transcriptional factor that has been demonstrated to be constitutively activated in several cancers, such as breast cancer, lung, colorectal and prostate cancers." (PMID 28514765, 2017). "Inhibitors of STAT3, β‐catenin, and IGF‐1R sensitized H1047R‐derived mouse tumor cells and PIK3CA‐H1047R overexpressing human HS578T breast cancer cells to the cytotoxic effects of PI3K inhibitors." (PMID 28296140, 2017).
breast cancer (continued). "MiR-124 suppresses tumour growth through targeting STAT3 in colorectal cancer, CD151 in breast cancer, and ERK in cutaneous squamous cell carcinoma." (PMID 29152130, 2017). "We performed RT-PCR to determine the expression levels of selected STAT3 target genes in FRK-overexpressing and the knockdown breast cancer cell lines." (PMID 29348886, 2017). "Jak/STAT3, ERK1/2, phosphoinositide 3-kinase pathways and cyclin D1 expression pathways are reported to be involved in mediating leptin-stimulated breast cancer cell growth." (PMID 28930270, 2017). "Inhibition of STAT3 by both curcumin and its analogue hydrazinocurcumin blocks protein expression of both Mcl-1 and Bcl-2 in MDA-MB-231 and MCF-7 breast cancer cells." (PMID 29262529, 2017). "Accidentally the positive correlation between STAT3 and CSE expression was observed in breast cancer tissues and cell lines." (PMID 29029463, 2017). "The Wnt/β‐catenin and Stat3 pathways were activated in PIK3CA‐H1047R breast tumors and human breast cancer cell line overexpressing mutant PIK3CA." (PMID 28296140, 2017). "Since STAT3 has been shown to stabilize HIF-1α upon hypoxia in Caki-1, a human renal carcinoma cell line and MCF-7, an estrogen receptor-positive breast cancer cell line, we asked if STAT3 is activated in our experimental model." (PMID 29036915, 2017). "Combination therapy of sorafenib and SC-2001 (Mcl-1 inhibitor) inhibited STAT3 activation by RFX-dependent SHP-1 reactivation and defeated the sorafenib resistance in HCC and breast cancer cells." (PMID 28594363, 2017). "Cks1 influences cell proliferation and apoptosis through activating the phosphorylation of MEK1/2 and ERK1/2 in breast cancer, and the phosphorylation of MEK1/2, ERK1/2 and STAT3 in multiple myeloma." (PMID 28061788, 2017). "Herein we show that the ShcA pathway simultaneously activates STAT3 immunosuppressive signals and impairs STAT1-driven immune surveillance in breast cancer cells." (PMID 28276425, 2017). "Because of the significant suppression of STAT3 activation by FRK (WT and Y497F), we checked if there was any correlation between FRK and pSTAT3 expression in a panel of 14 breast cancer cell lines." (PMID 29348886, 2017). "DOCK1 gene expression carries prognostic significance in breast cancer, ovarian cancer and glioblastoma multiforme through activation of c-JUN, STAT3, and Rac1." (PMID 29069784, 2017). "MiR-93 has also been found to inhibit EMT process of breast cancer cells through regulating MKL-1 and STAT3." (PMID 29245924, 2017). "Although FRK knockdown had little effect on STAT3 activation in SKBR3 and MCF-7 breast cancer cells, we noted that the knockdown of FRK led to the upregulation of Survivin mRNA levels in both cell lines." (PMID 29348886, 2017). "Specifically, OncoLead was highly effective in inferring novel breast-cancer-specific inhibitors of MYC and STAT3, which were experimentally validated." (PMID 29023443, 2017). "Strikingly, we found that TNF-α was able to up-regulate HBXIP through driving a positive feedback loop of NF-κB (and/or p38)/p-STAT3/HBXIP/TNFR1, resulting in the enhancement of growth of breast cancer." (PMID 28938560, 2017). "To test this possibility, we evaluated IL-6-mediated STAT3 phosphorylation in both control and PTPRD-silenced breast cancer cells." (PMID 29228728, 2017). "Collectively, we conclude that TNF-α increases STAT3 phosphorylation via NF-κB and/or p38 signaling in activation of HBXIP promoter in breast cancer." (PMID 28938560, 2017). "Interestingly, miR-7, which is inhibited by HOTAIR through the suppression of HoxD10, is downregulated in breast cancer CSCs and overexpression of miR-7 could both partially reverse EMT and decrease the size of the CSC population in breast cancer cell lines by suppressing STAT3 signalling." (PMID 28430163, 2017). "Given that MUC1 was specifically and significantly overexpressed in MT/Shc313F/313F breast cancer cells, we examined the relationship between MUC1 and STAT3 expression." (PMID 28276425, 2017).
breast cancer (continued). "JAK2 and STAT3 mutations both showed a trend toward being more frequent in distant metastasis samples, which may explain why these were detected as significant in our study but not in previous studies of primary breast cancer." (PMID 28810143, 2017). "A subsequent study further confirmed that STAT3 directly binds to the second proximal STAT-3-binding site on the human Twist1 promoter and activates its transcriptional activity in human breast cancer cell lines." (PMID 28099910, 2017). "On the other hand, miR-17-5p induced apoptosis in breast cancer cells, and overexpression of miR-17-5p sensitized MCF-7 cells to paclitaxel-induced apoptosis via STAT3." (PMID 28178652, 2017). "EGF activated STAT3 via gp130-independent EGFR and a strong correlation was found between nuclear STAT3 activation and EGFR expression in breast cancers through immunohistochemical analysis." (PMID 27861147, 2017). "Previous studies have demonstrated that STAT3 signaling mediated up-regulation of MMP-9 expression and conferred increased invasion ability in multi-drug-resistant breast cancer cells." (PMID 27793010, 2016). "In our study, the corresponding canonical cancer pathways in the HBL tumor transcriptome are GBM, Her-2 breast cancer, EGF and ERBB signaling (EGFR), Wnt-β-catenin signaling (Wnt), STAT3 and JAK/STAT signaling (JAK/STAT), and mTOR signaling pathways (mTOR)." (PMID 27910913, 2016). "Among the plethora of kinase receptors that stimulate STATs, janus kinases (JAK), in particular JAK2 driving STAT3 and STAT5 activation, have been reported to have significant roles in breast cancer." (PMID 27406745, 2016). "Treatment with lapatinib and S3I-201 increased radiation-induced cell death and decreased both radiation-induced STAT3 phosphorylation and survivin expression in HER2-positive SKBR3 breast cancer cells." (PMID 26755645, 2016). "In MCF-7 and SKBR3 breast cancer cells, pre-treatment with a LDFI-leptin receptor antagonist abrogated the leptin activation of Jak2, Stat3, Akt and ERK1/2 proteins." (PMID 27480179, 2016). "Increased EMMPRIN expression in activated fibroblasts increased the expression of STAT3 and HIF-1α and showed cancer stem-like cell features in breast cancer cells." (PMID 27325313, 2016). "In melanoma and breast cancer, CD276 has been reported to promote metastasis and chemoresistance through regulating JAK2/STAT3 signaling pathways and promoting the expression of cytokines and other metastasis-associated genes." (PMID 27329595, 2016). "The study for the first time indicated that cancer cells and fibroblasts interaction promotes breast cancer cells showing stem-like cells through up-regulation EMMPRIN, and led to inhibiting miR-106a/b expression which targets both STAT3 and HIF-1α expression." (PMID 27325313, 2016). "STAT3 inhibition increased MICA expression in human GBM and breast cancer cell lines as well, and STAT3 was shown to bind directly to a putative STAT-binding site in the MICA promoter." (PMID 27148255, 2016). "Endogenous STAT3 and HIF-1α expression in breast cancer cells with miR-106a/b transfection were examined." (PMID 27325313, 2016). "Thus, the observed upregulation of miR-96 in breast cancer may be due to activated STAT3." (PMID 27857177, 2016). "Since STAT3 can be activated by a variety of cytokines, including IL-11, CNTF, LIF and G-CSF, in breast cancer, it is crucial to identify those tumors that depend on IL-6." (PMID 27602583, 2016). "Our results indicate that imatinib exerts a significant inhibitory effect on breast cancer cell invasion and migration through inhibition of PDGFR and STAT3 phosphorylation, although the expression of PDGF-B was unchanged." (PMID 27259262, 2016). "STAT3 binds to and significantly activates theTWIST promoter in cooperation with EGF receptor(EGFR) in human breast cancer cells." (PMID 26862521, 2016).
breast cancer (continued). "DHA induced cell death in highly transformed SK-BR-3 breast cells with the reduction of ERK1/2 and STAT3 phosphorylation, but only slightly affected the cell cycle in MCF-7 breast cancer cells with a transformation degree lower than that in the SK-BR-3 cells." (PMID 27527148, 2016). "Inhibition of STAT3 by WP1066 decreased the incidence of BM and increased survival in a preclinical model of breast cancer BM." (PMID 26959886, 2016). "Another interesting study found that VEGFR-2 recruits JAK2/STAT3 to activate embryonic stem cell transcription factors MYC and SOX2 in breast cancer CSCs." (PMID 26500608, 2015). "In cancers of epithelial origin, STAT3 is constitutively activated in head and neck squamous cell carcinoma (HNSCC), breast cancer cell lines, ovarian cancer cell lines, lung cancer cell lines and myeloma cell lines." (PMID 26464811, 2015). "Inhibition of Stat3 via si-Stat3 or Stattic treatment also potentiated HNK-mediated inhibition of MTA1 and β-catenin expression in breast cancer cells." (PMID 26036628, 2015). "Consistently, STAT3 inhibitor treatment significantly suppresses the CSC-like OBRhi population and abrogates tumor progression of a diet-induced obesity rat model of breast cancer." (PMID 26501077, 2015). "Collectively, these results indicated that Shk inhibits multiple signaling proteins (STAT3, FAK and Src) to compromise various aggressive breast cancer hallmarks." (PMID 25973915, 2015). "In primary breast cancer samples, GRN mRNA levels were positively correlated with STAT3 gene expression signatures and with reduced patient survival." (PMID 26000098, 2015). "STAT5 and STAT3 are activated at different stages of mammary gland development and play distinct and reciprocal roles, but in a significant proportions of breast cancers, both STAT5 and STAT3 are activated." (PMID 26146825, 2015). "Collectively, these results suggest that PYK2 affects different migratory and invasive pathways in breast cancer cells in response to either EGF or HRG stimulation, but most profoundly affects the MAPK and STAT3 pathways." (PMID 26084289, 2015). "Surprisingly, in a subset of breast cancer cell lines enriched for the basal-like subtype, SYK inhibition impaired viability by reducing STAT3 activity." (PMID 25699542, 2015). "We analyzed a large number of breast cancer cell lines with Gene Expression-Based Outcome for Breast Cancer Online (GOBO), finding that TNBC and HER2-positive breast cancer cell lines express higher levels of YBX1 and STAT3." (PMID 26512918, 2015). "Here we demonstrated that CH12 had a significant growth-suppression effect on EGFRvIII+HER2+ breast cancers in vitro and in vivo at least partially through inhibiting the phosphorylation of EGFR, AKT and STAT3." (PMID 26474285, 2015). "We also show a unique role of Stat3 activation via VEGFR2 in orchestrating the interaction between endothelial and brain tumor cells and promoting breast cancer brain metastasis." (PMID 25881542, 2015). "Given that STAT3 is a well-known key pathway downstream of EGFR and an EMT promoter in breast cancer, we infer that the possible mechanism through which Anxa2 promotes EMT is dependent on the STAT3 pathway." (PMID 26307676, 2015). "This further supports the efficacy of Shk and STAT3 inhibition against stem cell and EMT programs in breast cancer." (PMID 25973915, 2015). "The elevated phosphorylation and activation of STAT3 is responsible for the enhanced invasive properties and upregulated expression of MMP-2 and -9 in SK-BR-3/EPR breast cancer cells." (PMID 26501276, 2015).